TET2 (tet methylcytosine dioxygenase 2)
Diseases named in the same sentence as TET2 in open-access papers (continued):
Sharing a sentence is not in itself a finding about the gene and the disease.
acute myeloid leukemia (continued). "TET2 mutations result in profound reductions of 5hmC, which are linked to adverse outcomes in disorders such as acute myeloid leukemia (AML) and myelodysplastic syndromes." (PMID 41243111, 2025). "Inactivating TET2 mutations are prevalent in acute myeloid leukemia (AML) and in other blood cancers." (PMID 40213851, 2025). "PARP inhibitors (e.g., olaparib) exhibit efficacy in TET2-mutant acute myeloid leukemia (AML), where TET2 loss impairs homologous recombination repair." (PMID 40917754, 2025). "It has also been reported that ectopic Hmga2 expression in adult HSPCs led to the development of acute myeloid leukemias (AML) in a Tet2-deficient context." (PMID 40143971, 2025). "Mutations in TET2 are strongly linked to various hematological cancers, such as acute myeloid leukemia (AML) and myelodysplastic syndromes (MDS)." (PMID 39519332, 2024). "In this article, we present a clinical case of MDS transformation into acute myeloid leukemia in the context of two cell lines exhibiting morphological, immunophenotypic, and dysmyelopoiesis markers and the presence of two heterozygous mutations in the TET2 gene." (PMID 38792657, 2024). "Somatic loss-of-function mutations of the dioxygenase Ten-eleven translocation-2 (TET2) occur frequently in individuals with clonal hematopoiesis (CH) and acute myeloid leukemia (AML)." (PMID 37816954, 2023). "This has been studied in acute myeloid leukemia (AML) in the case of TET2 mutations, which have been shown to be generally represented by loss-of-function mutations." (PMID 37998740, 2023). "Of note, IDH mutation reversibly sabotaged the demethylation function of TET2 via oncometabolite 2-hydroxyglutarate (2HG) in acute myeloid leukemia (AML)." (PMID 36203434, 2022). "Among these mutations, TET2 inactivating mutations are found in approximately 20% of MDS patients but are also seen in patients with acute myeloid leukemia (AML) and myeloproliferative neoplasms." (PMID 34622806, 2021). "Loss-of-function mutations in the DNA demethylase TET2 are associated with the dysregulation of hematopoietic stem cell differentiation and arise in approximately 10% of de novo acute myeloid leukemia (AML)." (PMID 34497762, 2021). "The evidence that in some tumors, such as AML (acute myeloid leukemia) TET2 and IDH mutations are mutually exclusive, support their involvement in the same pathway." (PMID 32806509, 2020). "The impact of Tet oncogene family member 2 (TET2) mutations on the prognosis of acute myeloid leukemia (AML) is still controversial." (PMID 31023266, 2019). "As the most frequently mutated member of TET family, TET2 is often mutated in both lymphoid malignancies (such as T cell lymphoma 30%–40%) and myeloid malignancies, especially acute myeloid leukemia (AML, 7%–23%)." (PMID 27548812, 2016). "TET2 mutations and isocitrate dehydrogenase (IDH) mutations are recurrent and mutually exclusive in the acute myeloid leukemia genome." (PMID 41403402, 2026). "We then analyzed patients with chronic myelomonocytic leukemia (CMML) or acute myeloid leukemia (AML) harboring TET2 and SRSF2 comutations." (PMID 40877435, 2025). "Indeed, mutations of the TET2 gene frequently occur in myeloid malignancies, including acute myeloid leukemia (AML) and chronic myeloid leukemia (CMML), among others, and are associated with a worse prognosis." (PMID 41169875, 2025). "Modulation of TET2 activity in mouse ESCs and in acute myeloid leukaemia (AML) cells reduces this repressive mark, reactivating young retrotransposons through increased m5C RNA levels." (PMID 40328728, 2025). "TET2 and GATA2 are two frequently co-mutated genes in CEBPA double mutated acute myeloid leukemia (AML)." (PMID 37794021, 2023).
acute myeloid leukemia (continued). "Treatment with the hypomethylating agents’ showed efficacy in myelodysplastic syndrome and acute myeloid leukemia, a response that appears to correlate with IDH1/2, TET2, and DNMT3A mutations." (PMID 37998740, 2023). "In high throughput genome‐wide studies, somatic deletion and loss of function TET2 mutations are detected in 7–23% of acute myeloid leukemia (AML), 10%–20% of myelodysplastic syndrome (MDS)/myeloproliferative neoplasms (MPN), and 40%–50% chronic myelogenous leukemia patients." (PMID 37601840, 2023). "Recent investigations highlighted the role of ascorbic acid as a critical regulator of cellular epigenetic processes, and a potential drug in the therapeutic armamentarium of acute myeloid leukemia through its stimulatory effect on TET2 function." (PMID 35938170, 2022). "TET2 expression is also a potential prognostic and predictive biomarker in cytogenetically normal acute myeloid leukemia." (PMID 33085059, 2021). "In acute myeloid leukemia patients, EZH2 mutations frequently co-occurred with CEBPA (67%), ASXL1 (50%), TET2 and RAD21 mutations (33% each)." (PMID 33845873, 2021). "The TET2 gene (tet oncogene family member 2) has been recently identified as a chief tumor suppressor gene in a number of myeloid disorders, including acute myeloid leukemia." (PMID 33643703, 2021). "The tet oncogene family member 2 (TET2) gene has been reported to be involved in DNA methylation and epigenetic regulation in acute myeloid leukemia (AML)." (PMID 33643703, 2021). "Mutations in TET2 and DNMT3A are also frequently associated with myeloid malignancies, including acute myeloid leukemia (AML), myeloproliferative neoplasms (MPN), and myelodysplastic/myeloproliferative neoplasms (MDS/MPN)." (PMID 34581268, 2021). "As the overexpression of BCAT1 is found in LSCs in TET2/Isocitrate dehydrogenase (IDH) wild-type acute myeloid leukemia, BCAT1 has been proposed as a driver of LSC self-renewal through its reduction of TET2 activity." (PMID 34830976, 2021). "Somatic mutations in Wilms' tumor 1 (WT1) and tet methylcytosine dioxygenase 2 (TET2) genes were separately perceived as contributors to hematopoietic disorders and usually thought to have a mutually exclusive effect in acute myeloid leukemia (AML)." (PMID 34120595, 2021). "MPNs are stem cell diseases: clonal evolution in acute myeloid leukemia occurs if additional mutations appear, such as ASXL1, TET2, DNMT3A, SF3B1, or SFSR2." (PMID 34684081, 2021). "TET2 and DNMT3A mutations were first described in myeloid neoplasms, such as acute myeloid leukemia (AML), myelodysplastic syndrome or chronic myelomonocytic leukemia (CMML), with CMML carrying the highest frequency of TET2 mutations." (PMID 32796826, 2020). "Also reflected is the report that a patient with B-cell lymphoma subsequently developed acute myeloid leukemia (AML); both the lymphoma and the AML harbored the same biallelic TET2 mutations." (PMID 33288848, 2020). "Among patients with U2AF1 gene mutations, those with ASXL1 mutations were prone to develop into acute myeloid leukemia, those with RUNX1 mutations had an increased risk of relapse, and those with TET2 mutations had higher 1-year survival rate." (PMID 33122737, 2020). "For instance, a striking example is the inducible deletion of both Tet2 and Tet3 in adult mice, which leads to acute myeloid leukemia with the mice succumbing as early as 3 weeks post-deletion." (PMID 30809228, 2019). "One of these RCTs was done in acute myeloid leukemia in a small group of patients treated with a hypomethylating agent (decitabine) that in vitro has a synergistic effect on vitamin C on TET2 expression, apoptosis and proliferation of tumor cells." (PMID 31035414, 2019). "Thus, TET2 protein has been implicated in the development of hematological malignancies such as acute myeloid leukemia (AML), chronic myelomonocytic leukemia (CMML), and Myelodysplastic syndrome (MDS)." (PMID 29623275, 2018).
acute myeloid leukemia (continued). "Especially in acute myeloid leukemia, translocation and mutations of TET1 and TET2 gene are frequently observed." (PMID 26833217, 2016). "In hematopoietic malignancies, including acute myeloid leukemias (AMLs), myeloproliferative neoplasms (MPN), myelodysplastic syndrome (MDS), and chronic myelomonocytic leukemia (CMML), TET2 gene has been shown to be frequently mutated." (PMID 27557497, 2016). "TET2 is a major factor in hematopoiesis, and several hematological malignancies, such as myelodysplastic syndrome, acute myeloid leukemia, or chronic myelomonocytic leukemia, have been linked to TET2 mutations." (PMID 27980696, 2016). "Inactivation of TET2 by genomic deletions or mutations has been reported in a wide range of adult hematological malignancies, including acute myeloid leukemia (AML), myelodysplastic syndrome (MDS) and myeloproliferative neoplasms (MPN), as well as in lymphoid malignancies." (PMID 25632305, 2015). "DNMT3A and TET2 are also candidate genes for CHIP mutations, as loss-of-function mutations in these genes are commonly detected in the peripheral blood samples of patients with myelodysplastic syndromes and acute myeloid leukemia." (PMID 40365343, 2025). "Common in both acute myeloid leukemia (AML) and myelodysplastic syndromes, TET2 mutations drive hypermethylation patterns similar to those produced by DNMT3A loss-of-function mutations using DNA demethylation by conversion of 5-methylcytosine to 5-hydroxymethylcytosine." (PMID 40581650, 2025). "Nonetheless, data on how much the overall survival of patients with acute myeloid leukemia correlates with TET2 mutations have been inconsistent, and hence no clear conclusion can be drawn." (PMID 39334883, 2024). "In contrast, in acute myeloid leukemia, apoptosis was inhibited by TET2 downregulation." (PMID 37371754, 2023). "In Acute Myeloid Leukemia, TET2 can activate lncRNA MEG3 transcription." (PMID 36969033, 2023). "Importantly, large cohort sequencing data suggest that individuals with TET2 mutations are also at a high risk of developing hematologic malignancies, such as myelodysplastic neoplasms, myeloproliferative neoplasms (MPN) and acute myeloid leukemia (AML)." (PMID 37816954, 2023). "In acute myeloid leukemia (AML), the IDH1/2 and TET2 mutations repel each other." (PMID 36428791, 2022). "Over 30 miRNAs were reported to inhibit TET2, regulating hematopoiesis of TET-2-wild-type (without mutation) acute myeloid leukemia compared to TET-2 mutant cells." (PMID 35269864, 2022). "TET1 was identified as a fusion partner of the mixed-lineage leukemia (MLL) gene from the breakpoint of chromosomal translocation in acute myeloid leukemia (AML), and loss of TET2 is strongly associated with myelodysplastic syndromes, myeloproliferative neoplasms, and myeloid leukemias." (PMID 33921666, 2021). "In addition, miR-7 can regulate TET2, which participates in the pathogenesis of acute myeloid leukemia by disrupting normal hematopoiesis." (PMID 32714094, 2020). "In hematologic malignancies, vitamin C treatment might enhance the enzymatic activity of TET2 to promote 5hmC formation and DNA demethylation in myelodysplastic syndrome or acute myeloid leukemia cells." (PMID 31730021, 2019). "Furthermore, we demonstrated that Tet2–/–;Flt3ITD acute myeloid leukemia (AML) precursors primarily underwent symmetric renewal divisions in culture." (PMID 29361987, 2018). "However, similar to NPM1 and FLT3 mutations in acute myeloid leukemia (AML), SRSF2 mutations seem to occur later in the development of myeloid neoplasms than TET2 mutations." (PMID 27029036, 2016). "TET2, a member of the ten-eleven-translocation (TET) family genes, located in chromosome 4q24, can mutate in various hematopoietic disorders, including myeloprolieferative neoplasms (MPNs), MDS, acute myeloid leukemia, and chronic myelomonocytic leukemia." (PMID 23691452, 2012).
acute myeloid leukemia (continued). "Somatic TET2 mutations are frequently reported in myeloid disorders, including myelodysplastic syndrome (MDS) and acute myeloid leukemia (AML)." (PMID 40116537, 2025). "TET2 mutations and loss of function have been reported in myeloid malignancies, including myeloproliferative neoplasm (MPN), acute myeloid leukemia (AML), secondary AML, myelodysplastic syndrome (MDS), and chronic myelomonocytic leukemia (CMML)." (PMID 40599235, 2025). "Somatic mutations in TET2 are frequently observed in various myeloid malignancies, including myelodysplastic syndromes (MDS), myeloproliferative neoplasms (MPN), and MDS/MPN overlap syndromes, including chronic myelomonocytic leukemia (CMML), acute myeloid leukemia (AML), and secondary AML (sAML)." (PMID 39519332, 2024). "Dysfunction in TET2 is well characterized in hematological malignancies including acute myeloid leukemia (AML) and myelodysplastic syndrome (MDS)." (PMID 38601144, 2024). "A 65-year-old woman was diagnosed with acute myeloid leukemia (AML-M2a subtype) on July 18, 2023,accompanied by mutations in FMS‐like tyrosine kinase 3 (FLT3)-ITD, NPM1, TET2, EZH2, and other genes." (PMID 39544304, 2024). "Interestingly, a subset of acute myeloid leukemia and glioma patients without TET2 mutations bear isocitrate dehydrogenases 1 and 2 (IDH1/2) mutations, which produce D-2-hydroxyglutarate to competitively inhibit TET2 activity." (PMID 37550284, 2023). "Information concerning the molecular role of TET2 mutation in cooperation with “driver” mutations has largely been garnered from genetic mouse models of acute myeloid leukemia (AML), including TET2–/–Flt3-ITD and TET2–/–AML-ETO mice." (PMID 35393954, 2022). "Patients with germline TET2 mutations were younger (median age 48, 16–82 years) (P = 0.0058) and mainly suffered from myelodysplastic syndromes (MDS) (n = 13, 39.4%), while patients with somatic TET2 mutations were mainly affected by acute myeloid leukemia (AML) (n = 26, 38.8%) (P = 0.0004)." (PMID 35279121, 2022). "TET2 increases the activity of HDAC2, and mutations of this gene have previously been described in other neoplasms such as AML (acute myeloid leukemia) with an unfavorable prognostic value." (PMID 32933053, 2020). "TET proteins were initially discovered when TET2 was found to be a part of a translocation protein with Mixed Lineage Leukemia (MLL) in a subset of patients with Acute Myeloid Leukemia (AML)." (PMID 31213988, 2019). "Regarding the MPN/AML transformation, mutations in genes encoding epigenetics modifiers such as ASXL1, IDH1, IDH2, EZH2, and TET2 are associated with nearly 30% of secondary leukemia transformations and de novo acute myeloid leukemia." (PMID 29515972, 2018). "TET2 mutations confer a worse prognosis in myelodysplastic syndromes (MDS) and acute myeloid leukemia (AML)." (PMID 26984174, 2016). "In acute myeloid leukemia (AML), mutations in DNA methylation regulators such as DNMT3A, TET2, IDH1 and IDH2 are frequent, and loss of function of TET2 and DNMT3A are early events in leukemogenesis." (PMID 26829670, 2016). "We have recently identified reduced TET2 mRNA expression in myelodysplastic syndromes (MDS) and acute myeloid leukemia (AML), which is associated with a poor overall survival in MDS." (PMID 26984174, 2016). "Acute myeloid leukemia (AML) with a normal karyotype (CN-AML), which accounts for 40–50% of AML cases, commonly presents with genetic mutations in ASXL1, MLL, DNMT3A, TET2, IDH1 and IDH2 genes, all of which have important roles in epigenetic regulation." (PMID 24202321, 2013). "Moreover, in pediatric acute myeloid leukemia (AML) a germline SNP in the epigenetic regulator gene TET2 (rs2454206) has been identified as a prognostic marker influencing survival outcomes." (PMID 40564131, 2025).
acute myeloid leukemia (continued). "For instance, mutations in DNMT3A and TET2 disrupt normal clonal hematopoiesis and are implicated in the transformation of HSCs into myelodysplastic syndromes (MDS) and acute myeloid leukemia (AML) 10-12." (PMID 40657362, 2025). "At the same time, other genetic alterations commonly found in acute myeloid leukemia, like DNMT3, TET2, NPM1, IDH1 or IDH2, are rarely detected, confirming the unique pathogenesis of APL." (PMID 38921185, 2024). "Given their self-renewal capacity, we hypothesized that B-1 cells may be regulated by TET2, an epigenetic modulator that has been implicated in the clonal expansion of hematopoietic cells leading to disorders such as myelodysplastic syndromes (MDS) and acute myeloid leukemia (AML)." (PMID 38601144, 2024). "TET2 mutations are associated with aberrant DNA methylation in a wide spectrum of myeloid malignancies, including myelodysplastic syndrome (MDS), myeloproliferative neoplasms (MPN), myelomonocytic leukemia (CMML), and acute myeloid leukemia (AML)." (PMID 36866275, 2023). "TET-2 mutations (Ten-eleven translocation 2) were originally described in myeloid malignancies, such as myelodysplastic syndromes (MDS), chronic myelomonocytic leukemias (CMML), and acute myeloid leukemias (AML)." (PMID 37182145, 2023). "TET2 was shown to acquire gain-of-function genetic alterations, especially in iso-citrate dehydrogenase 1 and 2 (IDH1 IDH2) in acute myelogenous leukemia (AML)." (PMID 35745630, 2022). "TET2 mutations often occur early during the development of human myeloid malignancies, including PV, ET, MF, myelodysplastic syndrome (MDS), chronic myelomonocytic leukemia (CMML), and acute myeloid leukemia (AML)." (PMID 34660059, 2021). "Mutated TET2 can promote and inhibit HSC differentiation, and loss of DNMT3A function could lead to transformation in acute myeloid leukemia (AML)." (PMID 34684081, 2021). "The highest frequency of Tet2 mutation occurs in chronic myelomonocytic leukemia (CMML) (30–60%), followed by myelodysplastic syndrome (MDS) (20–35%), acute myeloid leukemia (AML) (12–34%), and lymphoid malignancies (2–33%)." (PMID 34222235, 2021). "Recurrent TET2, DNMT3A, IDH1/2 mutations have been observed in patients with myeloproliferative neoplasms and other hematological malignancies, such as acute myeloid leukemia (AML), chronic myelomonocytic leukemia (CMML), or myelodysplastic syndromes (MDS)." (PMID 33803981, 2021). "In a range of myeloid and lymphoid neoplasms, the frequencies of TET2 mutations are 20–35% in myelodysplastic syndrome (MDS), 30–60% in chronic myelomonocytic leukemia (CMML), 12–34% in acute myeloid leukemia (AML) and 2–33% in lymphoid malignancies." (PMID 31001476, 2019). "Despite this, we observed a fully penetrant development of B cell lymphomas in all Tet2/3 DKO mice, consistent with our recent finding that acute deletion of Tet2 and Tet3 in hematopoietic stem/ precursor cells results in acute myeloid leukemia." (PMID 27869616, 2016). "In the last 3 years, alone mutations in the genes TET2, IDH1, IDH2, DNMT3a, and EZH2 have all been found in patients with myeloproliferative neoplasms (MPNs), myelodysplastic syndromes (MDSs), and/or acute myeloid leukemia (AML)." (PMID 21811504, 2012).